DDX5 (DEAD-box helicase 5)
Diseases named in the same sentence as DDX5 in open-access papers (continued):
Sharing a sentence is not in itself a finding about the gene and the disease.
gastric cancer (17 papers, 2017 to 2025). A primary or metastatic malignant neoplasm involving the stomach. "We observed frequently high expression of DDX5 and its strong association with p-mTOR in gastric cancer." (PMID 28216662, 2017). "This connection aligns with emerging evidence linking DDX5 to circRNAs function and biogenesis in other cancers, such as gastric cancer, where DDX5-driven circRNAs promote tumor growth and invasion." (PMID 40950397, 2025). "In this work, we determine that DDX5 is expressed at elevated levels within gastric cancer tissues and identify the effects of DDX5 in enhancing the growth and invasion of gastric cancer cells in vitro." (PMID 36996491, 2023). "DDX5-induced circRNAs have been found to be of crucial importance for the growth of DDX5-positive gastric cancer cells, providing a new therapeutic target." (PMID 36996491, 2023). "We also further examined the protein expression levels of DDX5 in multiple cell lines by western blot assay and found that the protein expression levels of DDX5 were generally higher in gastric cancer cells than in normal cells GES1." (PMID 36996491, 2023). "Next, the expression of DDX5 in normal tissues and gastric cancer patients was analysed in The Human Protein Atlas database." (PMID 36996491, 2023). "DDX5 overexpression notably accelerated the proliferation and growth of gastric cancer cells as shown by tumor cell clonogenesis assay, EdU staining and CCK8 cell proliferation assay." (PMID 36996491, 2023). "To further characterise the connection of DDX5 and gastric cancer, we analysed its expression in the gastric tissues of tumour patients." (PMID 36996491, 2023). "In gastric cancer, DDX5 contributes to the evolution of gastric cancer cells mediating the mTOR signaling pathway activation." (PMID 36996491, 2023). "According to our findings, DDX5 was dramatically upregulated for stomach cancer tissues, and its overexpression contributed to the cell growth and invasion of GC cells." (PMID 36996491, 2023). "Together, it is suggested that DDX5 stimulates the growth and migration on gastric cancer cells in vitro." (PMID 36996491, 2023). "Further to screen several circRNAs from PHF14 for function, it was found that circPHF14 was essential for the growth and tumorigenesis of DDX5-positive gastric cancer cells." (PMID 36996491, 2023). "In agreement with the results from public databases, DDX5 expression was higher in gastric cancer specimens than in normal specimens." (PMID 36996491, 2023). "For the purpose of testing the role of DDX5 in cell migration, we carried out transwell experiments in gastric cancer cells." (PMID 36996491, 2023). "In this research, through CircRNA-seq, we found that DDX5 induced the expression of a lot of circRNAs in gastric cancer cells, such as circPHF14." (PMID 36996491, 2023). "LINC01207 sponges miR-671-5p, inhibiting miR-671-5p targeting of DDX5 and promoting the development of gastric cancer." (PMID 35992805, 2022). "MIAT sponges miR-141, making it impossible for miR-141 to target DDX5, thus promoting the progression of gastric cancer." (PMID 35992805, 2022). "PSCA interacts with DDX5 and promotes DDX5 degradation through ubiquitination to inhibit the progression of gastric cancer." (PMID 35992805, 2022). "MSC-AS1 sponges miR-142-5p, rendering it unable to target DDX5 for degradation and promoting the development of gastric carcinoma." (PMID 35992805, 2022). "In vitro and in vivo studies suggested that knockdown of DDX5 inhibited gastric cancer cell proliferation, colony formation and xenografts growth, whereas ectopic expression of DDX5 promoted these cellular functions." (PMID 28216662, 2017). "The expression of DDX5 correlated strongly with Ki67 index and pathological stage of gastric cancer." (PMID 28216662, 2017). "This was further supported by the results of IHC and western blot analysis, which showed more expression of DDX5 protein in gastric cancer tissues." (PMID 28216662, 2017).
gastric cancer (continued). "Collectively, these data suggested that DDX5 played an important role in gastric cancer cell growth in vitro." (PMID 28216662, 2017). "Future work is clearly warranted to elucidate mechanistically how DDX5 regulates this pathway, and to validate the utility of DDX5 for gastric cancer therapy." (PMID 28216662, 2017). "We further identified the role of DDX5 in promoting gastric cancer cell growth in vitro and in vivo through lentivirus-mediated DDX5 up- or down-regulation models." (PMID 28216662, 2017). "In this study, we observed that DDX5 was significantly up-regulated in gastric cancer tissues compared with the paired adjacent normal tissues." (PMID 28216662, 2017). "In consistence with these studies, we also observed elevated expression of DDX5 in gastric cancer relative to the matched normal tissues." (PMID 28216662, 2017). "Inspired by these findings, we further explored the role of DDX5 in gastric cancer proliferation in vitro and in vivo." (PMID 28216662, 2017). "Intriguingly, we also observed a positive correlation between DDX5 and p-mTOR in gastric cancer tissues." (PMID 28216662, 2017). "The IHC staining of Ki67 further revealed that knockdown of DDX5 inhibited gastric cancer proliferation in vivo, while ectopic expression of DDX5 exhibited the opposite effects." (PMID 28216662, 2017). "Taken together, these results revealed a novel role of DDX5 in gastric cancer cell proliferation via the mTOR pathway." (PMID 28216662, 2017). "Real-time PCR analysis demonstrated increased expression of DDX5 mRNA (≥2 fold) as compared to normal tissue in 46 (70.7%) of the 65 gastric cancer samples." (PMID 28216662, 2017). "The expression of DDX5 significantly correlated with that of Ki67 in gastric cancer tissues, indicating a potential role of DDX5 in gastric cancer proliferation." (PMID 28216662, 2017). "To assess the functional role of DDX5 in gastric cancer cells, we established lentivirus mediated DDX5 up- and down-regulation systems in NCI-N87 and KATO III cell lines." (PMID 28216662, 2017). "In the present study, we determined the elevated expression of DDX5 in gastric cancer tissues compared with the matched normal tissues." (PMID 28216662, 2017). "As expected, knockdown of DDX5 inhibited gastric cancer cells proliferation in vitro and tumorigenesis in vivo." (PMID 28216662, 2017). "As revealed by western blot analysis, the expression of DDX5 and p-mTOR demonstrated a strong correlation in gastric cancer tissues." (PMID 28216662, 2017). "DDX5-induced circRNAs may have the function of enhancing the development of gastric cancer cells, which may offer new targets for subsequent diagnosis and treatment of DDX5-positive gastric tumor." (PMID 36996491, 2023). "To determine whether DDX5 and circPHF14 an extremely significant function in the development of gastric cancer cells in vivo, we established a xenograft nude tumor model." (PMID 36996491, 2023). "Although DDX5 and circRNA serve a very important function regarding the progression on gastric cancer, it is unclear whether DDX5 can participate in gastric cancer progression through the induction in circRNA expression." (PMID 36996491, 2023). "Moreover, we generated RNase R-treated RNA-seq data in AGS cells overexpressing DDX5 and identified a wealth of DDX5-induced circRNAs, in which circPHF14 enhances DDX5-positive gastric cancer cell growth and tumorigenesis in vivo and in vitro." (PMID 36996491, 2023). "Thus, high levels of MIAT result in inhibition of miR-141 synthesis and increased levels of DDX5, promoting cell proliferation and metastasis in gastric cancer." (PMID 35954483, 2022). "For instance, lncRNA PSCA can interact with DDX5 and promote its degradation in gastric cancer." (PMID 35608100, 2022).
gastric cancer (continued). "Additionally, it was reported that miR-5590-3p inhibited tumour growth in gastric cancer by targeting DDX5, and repressed diffuse large B cell lymphoma progression and immune evasion through targeting ZEB1 to regulate PD-1/PD-L1 checkpoint." (PMID 33088216, 2020). "Moreover, MIAT promotes gastric cancer growth and metastasis via regulation of the miR-141/DDX5 pathway." (PMID 33154765, 2020). "Accumulating evidence suggests that DDX5 is involved in carcinogenesis and progression, nevertheless, the functional role of DDX5 in gastric cancer is still unknown." (PMID 28216662, 2017). "First, we examined the expression of DDX5 in gastric cancer tissues." (PMID 28216662, 2017). "Interestingly, the expression of DDX5 and p-mTOR in gastric cancer tissues demonstrated a positive correlation." (PMID 28216662, 2017). "Moreover, we found that the expression of DDX5 increased significantly as gastric cancer progressed to more advanced stage." (PMID 28216662, 2017). "Taken together, these findings suggest that DDX5 plays a pivotal role in gastric cancer cell proliferation and might serve as a potential therapeutic target." (PMID 28216662, 2017). "Thus, we speculated whether DDX5 could promote the progression of gastric cancer cells via regulating the splicing formation of tumor-related circular RNAs." (PMID 36996491, 2023). "In gastric cancer (GC), MIAT sponges miR-141, leading to an increased expression of DEAD-box RNA helicase 5 (DDX5) and influencing GC cell proliferation and migration." (PMID 37624039, 2023). "Therefore, DDX5 may serve as a therapeutic target in gastric cancer." (PMID 28216662, 2017). "However, the functional role of DDX5 in gastric cancer is largely unknown." (PMID 28216662, 2017). "Therefore, targeting DDX5/mTOR/S6K1 might be a novel approach for the treatment of gastric cancer." (PMID 28216662, 2017). "Through The Cancer Genome Atlas database, we validated that DDX5 expression was significantly higher in gastric cancer samples than in non-tumour controls." (PMID 36996491, 2023). "In addition, tissues and cell lines of gastric cancer overexpress the lncRNA MIAT which sequesters the miRNA miR-141, a negative regulator of DDX5 expression." (PMID 35954483, 2022).
colon carcinoma (13 papers, 2017 to 2025). "DDX5 was determined to be overexpressed in colon cancer, and the degree of its expression was associated with progression of the disease from polyp to adenoma to adenocarcinoma." (PMID 30185232, 2018). "On the other hand, a treatment with oxaliplatin, an anticancer drug classified as a platinum preparation, phosphorylates DDX5 at T564 and/or T446 via p38, thereby inducing apoptosis in colon cancer cells." (PMID 38612503, 2024). "The increase in AKT transcription coupled with the depletion of the tumor suppressor FOXO3a (a downstream gene) accounts for the oncogenic role of DDX5 in colon cancer." (PMID 35954483, 2022). "It has been reported that the phosphorylation of DDX5 at Y593 is important for EMT in HT29 colon cancer cells." (PMID 33807895, 2021). "For example, phosphorylation of DDX5 at Y593 induced by c-Abl was reported to induce EMT in colon cancer cells." (PMID 33807895, 2021). "Our study suggests that PUM1 positively regulates DDX5 and acts as a promoter in cetuximab-resistant colon cancer cells." (PMID 34447749, 2021). "These experiments clearly demonstrated that PUM1 positively regulated DDX5 in cetuximab-resistant colon cancer cells." (PMID 34447749, 2021). "Western blot analyses revealed that DDX5 proteins were expressed at a significantly higher level in colonic tumors from APCΔcIEC mice than adjacent normal tissues or IECs from non–tumor-bearing WT mice, similar to findings previously reported in human CRCs." (PMID 32817263, 2020). "It was also found that PUM1 can positively regulate (DDX5) and increase cell viability, thus proving that the downregulation of PUM1 and DDX5 can reduce tumor cell viability and is a therapeutic target for the increased sensitivity of colon cancer to trastuzumab." (PMID 37020597, 2023). "In addition, in colon cancer, DDX5, β-catenin and NF-κB synergistically promote AKT gene transcription, which leads to the phosphorylation of the tumor suppressor FOXO3a and excludes it from the nucleus, causing it to be degraded in the cytoplasm." (PMID 35992805, 2022). "PRADX recruits the PRC2/DDX5 complex to promote glioblastoma and colon cancer." (PMID 35992805, 2022). "SUNO1 affects DDX5 to regulate the recruitment of RNA polymerase II to a the WTIP cis promoter, enhancing the transcription of WTIP, and promoting the development of colon cancer." (PMID 35992805, 2022). "We established cetuximab-resistant colon cancer cell lines SW480R and Caco-2R and knocked out PUM1 and DEAD-box helicase 5 (DDX5) with the clustered regularly interspaced short palindromic repeats (CRISPR)-caspase 9 (Cas9) system." (PMID 34447749, 2021). "A previous study revealed that DDX5, the homologous protein of DDX17, could directly interact with β-catenin to activate downstream gene transcription in colon cancer." (PMID 39897048, 2025). "In colon cancer, it was reported that overexpression of DDX5 upregulates the levels of the AKT protein and mRNA, increasing the transcription of the AKT gene promoter by DDX5 itself, β-catenin and NF-κB." (PMID 35954483, 2022). "Therefore, DDX5 or DDX17 is involved in the progression of various cancers (glioma, colon cancer, glioblastoma, colon adenocarcinoma, adult T-cell leukemia/lymphoma) by participating in the NF-κB signaling pathway." (PMID 35992805, 2022).
prostate carcinoma (13 papers, 2013 to 2023). A carcinoma that arises from epithelial cells of the prostate gland. "The tyrosine phosphorylation of DDX5 at Y593 caused by c-Abl contributes to the coactivation of androgen receptor and tumorigenesis in prostate cancer." (PMID 36593242, 2023). "CCAT1, as a scaffold linking DDX5 and AR transcription complex, promotes the development of castration-resistant prostate cancer." (PMID 35992805, 2022). "It has been shown that in prostate cancer (PC) DDX5 is highly expressed and promotes the proliferation of cancer cells." (PMID 35954483, 2022). "To reveal the potential impact of genomic rearrangements in the regulation of CCM1 and DDX5 genes, we explored 968 whole-genome sequences of PCa downloaded from four different cohorts including the Canadian prostate cancer genome network." (PMID 33807895, 2021). "As resveratrol degraded DDX5 protein and the depletion of DDX5 inhibited the mTORC1 pathway and growth of prostate cancer cells, we evaluated the significance of degrading DDX5 in the anticancer effects of resveratrol." (PMID 27148684, 2016). "We found that knockdown of DDX5 inhibited the growth and colony formation of hormone-refractory prostate cancer PC-3 and DU145 cells, similar to the treatment with resveratrol." (PMID 27148684, 2016). "The depletion of DDX5 protein resulted in growth inhibition and cell death by suppressing mTORC1 signaling in androgen-independent prostate cancer cells, similar to the treatment with resveratrol." (PMID 27148684, 2016). "To study the genome-wide contribution of Ddx5 and Ddx17 to the androgen-signaling pathway, we applied the same experimental strategy using the human LNCaP prostate cancer cell line that was treated with DHT for 24 h." (PMID 24275493, 2014). "The DEAD box RNA helicase p68 (Ddx5) is an important androgen receptor (AR) transcriptional co-activator in prostate cancer (PCa) and is over-expressed in late stage disease." (PMID 23349811, 2013). "For example, lncRNA CCAT1 acts as the scaffold of DDX5 and androgen receptor transcription complex to promote the expression of androgen receptor-targeted genes, which leads to a poor prognosis for patients with castration-resistant prostate cancer." (PMID 35992805, 2022). "As for MBNL1, the overexpression of DDX5 in prostate cancer could play a crucial role in the deregulation of the activity of RBFOX2 leading to cancer progression." (PMID 35954483, 2022). "Furthermore, several studies have shown that miRNAs can regulate the function of DDX5, such as the interaction of DDX5 with miR-28-5p in prostate cancer, or miR-431 regulation of the function of DDX5 in lung cancer." (PMID 34320120, 2021). "Interestingly, in a separate study, we identified DDX5 by mass spectrometry analysis as a PRMT5‐interacting protein in two prostate cancer cell lines (Dataset EV1)." (PMID 31267554, 2019). "Taken together, our results suggest that resveratrol suppresses mTORC1 signaling in androgen-independent prostate cancer cells by directly targeting DDX5, and 10 other resveratrol-binding proteins might also be druggable targets, similar to DDX5." (PMID 27148684, 2016). "Although DDX5 is overexpressed in prostate cancer and functions as a co-activator of the androgen receptor, its functions in hormone-refractory prostate cancer remain unknown." (PMID 27148684, 2016). "Thus, DDX5 overexpression in prostate cancer might lead to the inhibition of the oncosuppressor activity of MBNL1." (PMID 35954483, 2022). "Studies have shown that there is an increase in DDX5 and DDX17 expression levels in breast, cervix, colon, and prostate cancer." (PMID 35237661, 2022). "Although depletion of DDX5 was reported to induce apoptosis by downregulating Notch1 signaling in lymphoblastic leukemia cells, Notch1 signaling was not suppressed by DDX5 depletion in prostate cancer cells." (PMID 27148684, 2016).